MNMIP1 (manchette microtubule inner protein 1)
Synonyms: SH3D21; C1orf113; FLJ22938
Tractability: Antibody: the Human Protein Atlas places it where antibodies can reach. PROTAC: ubiquitination databases record sites on it.
Gene: Protein-coding gene on chromosome 1 (36,306,368 to 36,329,340, forward strand). Ensembl gene ENSG00000214193.
Subcellular location (Human Protein Atlas): Plasma membrane; Basal body; Nucleoplasm
Gene Ontology:
Molecular function: protein-macromolecule adaptor activity
Biological process: actin filament organization; cell migration
Genetic constraint (gnomAD): Loss-of-function variants: 81 observed, 79.81 expected, observed/expected ratio (o/e) 1.01, 90% interval 0.85 to 1.22. The upper end of that interval is the gene's LOEUF score, 1.22, which puts it in group 5 of 6, group 1 being the genes least tolerant of losing a copy. Missense variants: 975 observed, 964.36 expected, observed/expected ratio (o/e) 1.01, 90% interval 0.96 to 1.07. Synonymous variants: 383 observed, 392 expected, observed/expected ratio (o/e) 0.98, 90% interval 0.9 to 1.06.
Homologues: Orthologues: chimpanzee SH3D21 (98% identical), macaque SH3D21 (92% identical), dog SH3D21 (58% identical), mouse Sh3d21 (50% identical), rat Sh3d21 (42% identical), tropical clawed frog sh3d21 (20% identical), zebrafish sh3d21 (19% identical), Drosophila melanogaster cindr (18% identical), Caenorhabditis elegans cdap-2 (13% identical). Paralogues in human: SH3KBP1 (21% identical), CD2AP (20% identical), NOSTRIN (6% identical).
Diseases named in the same sentence as MNMIP1 in open-access papers:
MNMIP1 is named in the same sentence as 16 diseases in open-access papers, as found by Europe PMC text mining. Sharing a sentence is not in itself a finding about the gene and the disease.
MNMIP1 shares sentences with these, for which no sentence is quoted: pancreatic cancer (4 papers); cancer (3); lung carcinoma (2); Alzheimer disease (1); ataxia-telangiectasia and (1); colorectal cancer (1); dementia (1); hepatocellular carcinoma (1); infertile (1); male infertility (1); mammary tumor (1); myeloma (1); Obesity (1); oral cancer (1); Parkinsonism (1); tumor (1).